EZH2 (enhancer of zeste 2 polycomb repressive complex 2 subunit)
Diseases named in the same sentence as EZH2 in open-access papers (continued):
Sharing a sentence is not in itself a finding about the gene and the disease.
Obesity (13 papers, 2011 to 2025). Accumulation of substantial excess body fat. "EZH2 has been implicated in multiple diseases such as cancer, obesity, and skin disease." (PMID 36086687, 2022). "This review provides the latest knowledge about the involvement of EZH2 in the process of adipogenesis and obesity involving adipocyte differentiation, extract key concepts, and highlight open questions toward a better understanding of EZH2 function and the molecular mechanisms underlying obesity." (PMID 36086687, 2022). "Recent studies have highlighted the involvement of Ezh2 and associated histone modifications in maternal HFD and obesity on fetal organogenesis." (PMID 39798880, 2025). "This review summarizes recent advances in EZH2-mediated regulation of adipogenesis and obesity, breaking new grounds for a better and deeper understanding of the molecular mechanisms underlying adipogenesis and the occurrence and progression of obesity." (PMID 36086687, 2022). "TRAF6, an adaptor protein that possesses E3 ubiquitin ligase activity, is increased in HFD-induced obesity and increases ubiquitination and degradation of EZH2 to reduce EZH2 level." (PMID 34681631, 2021). "Emerging evidence has shown the important role played by EZH2 in adipogenesis and obesity." (PMID 36086687, 2022). "The EZH2 knockout mice exhibit better tolerance to diet-induced obesity and insulin resistance." (PMID 36086687, 2022). "Liu et al15 found that circSAMD4A could control the occurrence of obesity through the miR‐138‐5p/EZH2 axis." (PMID 33219594, 2022). "Interestingly, previous evidence has suggested that tumor necrosis factor (TNF), receptor-associated factor 6 (TRAF6), and enhancer of the zeste homolog 2 (EZH2) are key players in the upregulation of miR-429-3p in HFD-induced obesity." (PMID 34681631, 2021). "Therefore, it is suggested that enhancement of TRAF6 expression in obesity could increase degradation of EZH2, thereby promoting upregulation of miR-429-3p." (PMID 34681631, 2021). "Our study links EZH2‐H3K27me3 with the decrease of MANF and provides a direction for finding effective therapeutic strategies for treating the paternal obesity‐induced transgenerational glucose metabolic dysfunction." (PMID 40041941, 2025). "Yet, we cannot rule out the contribution of other epigenetics enzymes (e.g., EZH2, HAT1, LSD2, H3K4me3, H3K9me3, and H3K27me3), previously reported to be elevated in obese-MSCs, to alter mitochondrial gene expression and function imposed by obesity." (PMID 38824145, 2024). "Herein, our findings suggest that in obesity, miR-138-5p could interact with the 3'UTR of EZH2, as confirmed by the dual luciferase assay, and also inhibit its expression, thereby suppressing preadipocyte differentiation." (PMID 32292524, 2020). "We supposed androgens may act as an intermediary for the close correlation between androgens and obesity and androgens, function on the expression of DAB2IP by suppressing EZH2 expression." (PMID 22046421, 2011). "FF with increased S6K1-mediated EZH2-induced H3K27me3-mediated WNT suppression might thus overstimulate MSCs to enter ASC commitment, paving the way to obesity, whereas BF apparently controls the appropriate postnatal magnitude of Wnt signaling in the ASC vascular niches." (PMID 40429638, 2025). "Furthermore, the EZH2 inhibitor GSK126 inhibits the differentiation of MEFs into white adipocytes but promotes their differentiation into brown/beige adipocytes and alleviates the obesity phenotype by promoting the differentiation of thermogenic beige adipocytes in diet-induced obese mice." (PMID 40429638, 2025).
T-cell acute lymphoblastic leukemia (13 papers, 2015 to 2024). Acute lymphoblastic leukemia of T-cell origin. "Loss-of-function mutations in EZH2, EED, or SUZ12 occur in a subset of myeloid malignancies, T-cell acute lymphoblastic leukemia (T-ALL), and malignant peripheral nerve sheath tumors (MPNSTs)." (PMID 37051671, 2023).
Autoimmunity (12 papers, 2015 to 2024). The occurrence of an immune reaction against the organism's own cells or tissues. "Given that the effector program was exaggerated in Ezh2-deficient cells, we expected that the cells would be more aggressive in mediating host defense and autoimmunity." (PMID 26090605, 2015). "Thus, loss of EZH2 function and consequently Treg dysfunction may drive pathophysiological mechanisms of particular autoimmune disorders." (PMID 30619315, 2018). "Previous studies have indicated that the interaction between USP7 and EZH2 can also play a role in the regulation of immune response and inflammation, processes that are relevant to conditions such as autoimmunity and cancer." (PMID 39310812, 2024). "But inhibiting EZH2 can also impair the suppressive functions of Tregs, which can lead to spontaneous autoimmunity." (PMID 36313363, 2022). "Ezh2 is not only involved in autoimmunity; its expression and contribution to cellular dysregulation have been demonstrated in numerous studies of malignant cells." (PMID 32503684, 2020). "EZH2 is required to promote the FOXP3-mediated gene repression program following TCR stimulation.Loss of EZH2 in Tregs in vivo leads to multi-organ inflammation and increases susceptibility to experimental models of autoimmunity." (PMID 30619315, 2018). "Despite the differences in cytokine gene expression and iTreg development that we found in vitro, Ezh2-deficient mice did not develop spontaneous autoimmunity." (PMID 26090605, 2015). "Based on evidence from in vivo studies in mice in the context of EZH2 deletion in T cells, effector Th cell dysfunction is consistent across all disease models, evidently through impaired clearance of pathogens or aggravated autoimmunity (potentiated tissue destruction)." (PMID 30619315, 2018). "Our observations further highlight the fundamental role of Ezh2 in regulating IRF4 and IRF8 in tolerogenic DCs and limiting autoimmunity." (PMID 32899608, 2020). "In mice, it was shown that EZH2 expression was induced in a CD28-dependent manner and the mutant mice bearing Treg-specifically depletion of EZH2 developed fetal multi-organ autoimmunity with excessive T cell activation." (PMID 29619032, 2018). "We and others have demonstrated that mice lacking EZH2 in natural FOXP3+ Tregs developed spontaneous multi-organ inflammation and were more susceptible to experimental models of autoimmunity." (PMID 30619315, 2018). "Thus, the absence of autoimmunity in the face of defective Treg cell function in mice lacking EZH2 in CD4 cells is explained by the concomitant defects in effector T cells." (PMID 26090605, 2015). "Thus under inflammatory conditions such as infection and autoimmunity, EZH2 is critical to maintain T cell homeostasis irrespective of their lineage and function." (PMID 26090605, 2015). "The lack of autoimmunity and polyclonal B cell activation in CD4.Ezh2-KO T cell-induced cGVHD could be due to T cell unresponsiveness, T cell failure to stimulate B cell responses, or a failure of activate autoreactive B cells." (PMID 32503684, 2020).
bladder tumors (12 papers, 2015 to 2025). "Genetic alterations that frequently occur in bladder tumors, for example, Rb1 loss and c-myc amplification, also drive EZH2 expression and activity." (PMID 30692641, 2019). "Therefore, we conclude that epigenetic therapy targeting EZH2 alone or in combination with cisplatin can be beneficial in bladder tumors with KDM6A and/or SWI/SNF mutations and/or increased EZH2 activity." (PMID 30692641, 2019). "Collectively, this study provides molecular evidences indicating that the gene expression rewiring occurring in primary bladder tumors, associated with increased EZH2 expression and activity and mediating the increased recurrence and progression risk, are prevented by PIK3CA-dependent signaling." (PMID 28060766, 2017). "We also found that following the surgical removal of bladder tumors, the serum levels of EZH2 showed a significant decline." (PMID 38476362, 2024). "Whole transcriptional analyses of mouse and human bladder tumours showed that EZH2 had significant overlap in function, and confirmed that EZH2 played a critical role in the down-regulation of gene expression programs." (PMID 30542123, 2018). "This indicates that the elevated serum EZH2 levels might indeed stem from the bladder tumor tissues." (PMID 38476362, 2024). "Therefore, EZH2 inhibition, delayed tumor onset in KDM6A-null cells and caused regression of KDM6A-null bladder tumors in multiple mouse models." (PMID 39118085, 2024). "Therefore, patients who can potentially benefit from EZH2 inhibition would include those whose bladder tumors possess KDM6A and SWI/SNF mutations, Rb1/c-myc alterations and post-translational modifications of EZH2." (PMID 30692641, 2019). "EZH2 inhibition upregulated UTX-EZH2 target genes and contributed to the EZH2-dependent growth suppression in KDM6A-null bladder tumors in both patient-derived and cell line xenograft models." (PMID 31221981, 2019). "For example, the elevated expression level of EZH2 is a common event in UBC samples, and correlates with aggressiveness and invasion of bladder tumors." (PMID 26484567, 2015).
bladder urothelial carcinoma (12 papers, 2010 to 2021). "Taken together, our preliminary in vitro data do neither support the concept of an anti-regulation between ARID1A and EZH2 in urothelial cells nor ARID1A-deficiency as a suitable predictive biomarker for EZH2-inhibitor treatment response in urothelial bladder cancer." (PMID 30138427, 2018). "Transfection of miR-101-3p mimics also sensitized bladder urothelial carcinoma cells to cisplatin via inhibiting enhancer of zeste homolog 2 (EZH2) expression." (PMID 34694211, 2021). "The results showed that the expression of EZH2 was up‐regulated in various tumours (liver hepatocellular carcinoma, bladder urothelial carcinoma, colon adenocarcinoma, etc) compared with normal tissues." (PMID 32725802, 2020). "Taken together, we assume that ARID1A-deficiency (ARID1A truncating mutations and/or expression loss) is not a suitable predictive biomarker for EZH2 inhibitor treatment response in urothelial bladder cancer." (PMID 30138427, 2018). "Moreover, miR-101 is down-regulated in bladder transitional cell carcinoma, and directly represses EZH2." (PMID 26633386, 2015). "Scholars have reported that EZH2 can repress multiple downstream targets (e.g., KDM6A, GIT1) directly by binding to their promoter regions contributed to the progression of urothelial bladder carcinoma." (PMID 34776951, 2021). "Moreover, a synthetic lethality relationship between other SWI/SNF components including ARID1A and EZH2 has been revealed in several tumor entities but the potential of this concept for urothelial bladder cancer therapy is not known." (PMID 30138427, 2018). "ARID1A: No predictive biomarker for EZH2-inhibitor treatment response in urothelial bladder cancer?" (PMID 30138427, 2018).
chronic lymphocytic leukemia (12 papers, 2014 to 2024). "Moreover, in chronic lymphocytic leukemia, microenvironment-induced NF-ΚB regulates genes associated with cell cycle, reactive oxygen species (ROS), and protein stability, resulting in suppression of RB and induction of EZH2." (PMID 31752930, 2019). "A recent study from our group implicated for the first time EZH2 in the pathophysiology of chronic lymphocytic leukemia (CLL), a chronic malignancy of mature B cells, displaying remarkable clinical and biological heterogeneity." (PMID 27191993, 2016). "Another study has reported that EZH2 can upregulate PI3K/AKT signalling pathway to aggravate chronic lymphocytic leukaemia." (PMID 37698037, 2023). "Here we investigated the expression and functionality of EZH2 in chronic lymphocytic leukemia (CLL)." (PMID 27191993, 2016). "Additionally, EZH2 has actions that induce the PI3K/AKT pathway in clinically aggressive chronic lymphocytic leukemia, and it modulates the cardioprotective effects of mesenchymal-stem-cell-secreted exosomes via HMGA2-mediated PI3K/AKT signaling." (PMID 37445833, 2023). "Importantly, we find that activation of NF-κB also induces EZH2 expression in CD40L stimulated cells from Chronic Lymphocytic Leukemia patients." (PMID 25255445, 2014). "Interestingly, we find that CD40 ligand stimulation of cells from Chronic Lymphocytic Leukemia patients, which strongly induces the alternative NF-κB pathway, also induces EZH2 expression." (PMID 25255445, 2014). "A study demonstrated the elevated expression of EZH2, c-Myc, E2F1, and pRb proteins and decreased miR-26a expression in the proliferation centers (PCs) of CLL/small lymphocytic lymphoma (SLL)." (PMID 38492089, 2024). "Furthermore, the MYC-mediated miR-29 repression mechanism for the therapy of aggressive B-cell malignancies (B-cell malignancies is the synonym of chronic lymphocytic leukemia according to Medical Subject Headings (MeSH)) by applying the HDAC3 and EZH2 as therapeutic targets was reported." (PMID 28340554, 2017).
Anxiety (11 papers, 2019 to 2025). Intense feelings of nervousness, tension, or panic often arise in response to interpersonal stresses. "Collectively, these findings suggest a causal link between EZH2‐mediated epigenetic changes and the anxiety‐like phenotype associated with AUD." (PMID 41190727, 2025). "EZH2 was selected as the target gene of miR-124-3p in IBS-like rats because EZH2 is associated with anxiety and pain." (PMID 36467610, 2022). "Here our results suggest that the loss of miR-137 in the forebrain potentially causes anxiety by highly elevated EZH2." (PMID 31736707, 2019). "Hence, raising miR-101a-3p expression in the amygdala raises anxiety-like behaviour and this is at least partly caused by the repression of Ezh2." (PMID 35938156, 2022). "Together our results suggest that loss of miR-137 contributes to the etiology of anxiety, and EZH2 might be a potential therapeutic target for anxiety and depressive phenotypes associated with the dysfunction of miR-137." (PMID 31736707, 2019). "The knockdown of Ezh2 via siRNA infusion into the CeA prevented AIE‐induced anxiety‐like behaviour, normalized H3K27me3 and H3K27ac levels at the Arc SARE site and restored ARC expression." (PMID 41190727, 2025). "Neuronal-specific EZH2 knockout exhibited only a weak trend toward improvement in gut microbiota—mediated anxiety-like behaviors, suggesting a potential, albeit limited, link between EZH2 and anxiety phenotypes." (PMID 41041075, 2025). "It has been shown that increasing miR-101a-3p expression in the amygdala increases anxiety-like behavior, which is at least partially mediated via changes in EZH2 expression in an inbred strain of rat that has a high-response to novelty." (PMID 38670959, 2024). "Here, to determine if there is a sex-specific difference in epigenetic modifications and expression of Arc gene, we evaluated the role of EZH2 in the CeA in driving anxiety-like behavior in adulthood after AIE." (PMID 38670959, 2024). "The upregulation of circKcnk9 strongly suppresses the activity of miR124-3p, leading to increased expression of the target gene EZH2, which in turn results in VH and anxiety." (PMID 38967892, 2024). "The present study describes a direct role of EZH2 in regulating an anxiety-like phenotype in adulthood that develops after AIE in both male and female rats." (PMID 38670959, 2024). "We also observed that knockdown of EZH2 prevents AIE-induced anxiety-like behavior and reductions in Arc expression in the amygdala of both male and female adult rats." (PMID 38670959, 2024). "EZH2 siRNA infusion into CeA attenuated AIE-induced anxiety-like behaviors in the EPM test in both male and female rats." (PMID 38670959, 2024). "Our data indicate that an EZH2-mediated epigenetic mechanism in the CeA plays an important role in regulating anxiety-like behavior and Arc expression after AIE in both male and female rats in adulthood." (PMID 38670959, 2024). "Using a siRNA approach, researchers discovered that direct knockdown of Ezh2 increased anxiety-like behavior in high-novelty responding rats, but to a lesser extent than miR-101a-3p overexpression." (PMID 36979479, 2023). "Then, through stereotaxic administration of siEZH2 into CA1 to knock down EZH2, its effects on visceral hypersensitivity, anxiety, and CA1 LTP were examined." (PMID 36467610, 2022). "In light of our finding that CA1 EZH2 expression was increased in IBS-like rats, we microinjected siEZH2 into CA1 to knock down EZH2 and examine its effects on visceral hypersensitivity, anxiety, and CA1 LTP." (PMID 36467610, 2022). "EZH2 is a target gene of CircKcnk9/miR-124-3p and affects visceral hypersensitivity and anxiety in IBS-like rats by modifying CA1 LTP." (PMID 36467610, 2022). "Ezh2 knockdown with short-interfering RNA also increased HR’s anxiety-like behaviour, but to a lower level than with miR-101a-3p overexpression." (PMID 35938156, 2022).